SAMSN1 (SAM domain, SH3 domain and nuclear localization signals 1)
Diseases named in the same sentence as SAMSN1 in open-access papers (continued):
Sharing a sentence is not in itself a finding about the gene and the disease.
periodontitis (2 papers, 2021 to 2023). An acute or chronic inflammatory process that affects the tissues that surround and support the teeth. "In addition, recent research demonstrated that SAMSN1 is a biomarker crosstalk gene between periodontitis and venous thromboembolism." (PMID 37786523, 2023). "Therefore, the relation between SAMSN1 and periodontitis appears plausible." (PMID 34925639, 2021). "Four potential biomarker crosstalk genes were also immune genes, i.e., LGALS1, LSP1, SAMSN1, and WIPF1 between periodontitis and VTE." (PMID 34925639, 2021). "Four biomarker crosstalk genes between periodontitis and VTE were also immune genes, i.e., LGALS1, LSP1, SAMSN1, and WIPF1." (PMID 34925639, 2021). "Similar as for LSP1, no studies reported the role of SAMSN1 in periodontitis or VTE, yet." (PMID 34925639, 2021).
Sepsis (2 papers, 2020 to 2024). Sepsis is defined as life-threatening organ dysfunction caused by a dysregulated host response to infection. "In contrast, the overexpression of macrophage SAMSN1 ameliorates LPS-induced sepsis lung injury in mice." (PMID 39712019, 2024). "Moreover, research has established that macrophage Sprouty4 (Spry4) and SAMSN1 modulate sepsis-induced lung injury via the AMPK pathway." (PMID 39712019, 2024).
B-cell lymphoma (1 paper, 2021). "Two of these genes, IMPDH2 and SAMSN1 are highly expressed genes in our list of biomarker candidates for B-cell lymphoma." (PMID 34570764, 2021).
Hepatic steatosis (1 paper, 2012). Steatosis is a term used to denote lipid accumulation within hepatocytes. "However, body weight and resistance to HFD-induced obesity and hepatic steatosis have not been specifically analyzed in either heterozygous or homozygous Samsn1 mice." (PMID 22276124, 2012).
leukemia (1 paper, 2020). A malignant (clonal) hematologic disorder, involving hematopoietic stem cells and characterized by the presence of primitive or atypical myeloid or lymphoid cells in the bone marrow and the blood. "HACS1 (SLy2, SAMSN1, NASH1, SASH2) is a signaling adaptor protein that was first associated with leukemia." (PMID 33188360, 2020).
malaria (1 paper, 2021). Malaria is a serious and sometimes fatal disease caused by a parasite that commonly infects a certain type of mosquito which feeds on humans. "Within the nine genes, five genes (MBP, SAMSN1, PSMF1, SLC39A8, and EIF3B) were previously found to be involved in malaria, and the remaining four genes (SMPDL3A, FABP5, SPSB3, and SHARPIN) were identified for the first time in the current study." (PMID 33942992, 2021). "Among nine key genes, four genes (SAMSN1, SLC39A8, SMPDL3A, and FABP5) were positively correlated with malaria severity and upregulated in CM." (PMID 33942992, 2021). "SAMSN1, SLC39A8, SMPDL3A, and FABP5 were positively correlated with malaria phenotype/severity and showed an upregulation in the CM group compared with healthy controls, while MBP, SPSB3, PSMF1, SHARPIN, EIF3B were negatively correlated with malaria severity and downregulated in the DEG." (PMID 33942992, 2021).
metastatic tumor (1 paper, 2020). "Neither the upregulation of SAMSN1 by transgenic overexpression, nor the downregulation of SAMSN1 by CRISPR‐mediated genome editing, affected the growth of metastatic tumors of human MM cell lines within the BM of immunodeficient NSG mice." (PMID 32923989, 2020).
Renal cyst (1 paper, 2017). A fluid filled sac in the kidney. "So far, TDS did not exhibit renal cyst phenomenon by ultrasound diagnosis, while the SAMSN1 gene expression in TDS displayed a relatively low level like ADPKD patients." (PMID 28927462, 2017).
squamous cell carcinoma (1 paper, 2022). A carcinoma arising from squamous epithelial cells. "The PFS of the patients with high SAMSN1 expression was longer than that of the patients with low SAMSN1 expression; which showed with responders in squamous cell carcinoma." (PMID 35135489, 2022).
tumor (17 papers, 2013 to 2025). "To test the function of Samsn1 in tumor-associated macrophages in vivo, we injected either wild-type or Samsn1-/- ex vivo polarized M2 macrophages into established 5TGM1 tumors." (PMID 26020268, 2015). "Moreover, CD163, TNFAIP2, and SAMSN1 displayed a robust association with survival outcomes that remained significant independently of key clinical parameters such as gender, age at diagnosis, tumor content (%), and disease stage." (PMID 39015503, 2024). "Accumulating evidence shows that SAMSN1 is differentially expressed in many tumors and is related to tumor progression and prognosis." (PMID 37786523, 2023). "We conclude that the reported potent in vivo tumor suppressor activity of Samsn1 can be attributed, in large part, to graft‐rejection from Samsn1−/− recipient mice." (PMID 32923989, 2020). "In support of this, the introduction of Samsn1 into the KaLwRij‐derived MM PC 5TGM1 line was shown to abrogate tumor development in vivo." (PMID 32923989, 2020). "It was unexpected that expression of Samsn1, which is a foreign protein in Samsn1−/− KaLwRij mice, would elicit an immune response that was capable of completely abrogating tumor growth in vivo." (PMID 32923989, 2020). "This constituted a significant inhibition of tumor penetrance for 5TGM1‐Samsn1 cells compared to 5TGM1‐EV control cells in the C57BL/6/Samsn1−/− mice (p = 0.0207, Fischer's exact test)." (PMID 32923989, 2020). "While the abrogation of tumor development by Samsn1 in the 5TGM1/KaLwRij model suggested it was a potent tumor suppressor in MM, the mechanism(s) by which Samsn1 achieved this anti‐tumor effect was unclear." (PMID 32923989, 2020). "One such tumor suppressor gene is SAMSN1, which was found to have reduced expression in several different cancer types." (PMID 32923989, 2020). "Taken together, these data demonstrate that Samsn1 regulated B-cell proliferation in non-tumor bearing mice and restrained MM tumor cell growth in part through a plasma cell intrinsic mechanism." (PMID 26020268, 2015). "As a tumor suppressor gene, the decreased expression of SAMSN1 was found in several cancers." (PMID 39015503, 2024). "In Il18−/− mice, the expression of Samsn1 is significantly decreased, suggesting that tumor growth might be promoted." (PMID 38139000, 2023). "Here, using a panel of SAMSN1/Samsn1 knockdown and transgenic cell lines and multiple mouse strains, we set out to further investigate the conditions under which SAMSN1 expression so potently abolishes tumor growth in vivo." (PMID 32923989, 2020). "Our group and others have previously identified the adaptor protein SAMSN1 as a novel tumor suppressor in MM, the downregulation of which may promote MM development." (PMID 32923989, 2020). "This suggested that there may be a mechanism, other than intrinsic inhibition of MM PC proliferation, by which Samsn1 inhibits tumor growth in vivo." (PMID 32923989, 2020). "In relation to human MM, SAMSN1 mRNA expression was found to be significantly reduced in the PCs of MM patients compared to healthy individuals, which was also consistent with SAMSN1 having a tumor suppressor role in MM patients." (PMID 32923989, 2020). "Upregulation of genes such as POSTN, TNFSF13B and SAMSN1 could provide increased metastatic potential of the tumour, as discussed." (PMID 27358011, 2016). "Involving other clinical parameters such as age at diagnosis, gender, and tumor content (%) in Cox survival analysis model 2, ITGAX,SAMSN1, TNFAIP2 and CD163 showed significant values." (PMID 39015503, 2024). "Samsn1‐expressing or EV control 5TGM1 cells were injected i.v. into C57BL/6 mice, which were then monitored for tumor development over 7 weeks." (PMID 32923989, 2020).
tumor (continued). "Immunohistochemical results suggested that in tumor tissues, CASP8 and SAMSN1 showed high staining, TXNIP showed medium staining, while KLF6 and XCL1 showed negative staining; in normal tissues, KLF6 showed medium staining, CASP8 and SAMSN1 showed low staining, while TXNIP showed negative staining." (PMID 40149637, 2025). "For LP‐1 cells, SAMSN1 overexpression did not significantly affect tumor burden either in the injected tibia (p = 0.0667, Mann–Whitney U test), or the non‐injected leg (p = 0.5273, Mann–Whitney U test)." (PMID 32923989, 2020). "Samsn1 expression in the 5TGM1 tumor cells was found not to affect tumor penetrance in mice, as determined by BLI or SPEP (p > 0.9999, Fisher's exact test)." (PMID 32923989, 2020). "Unexpectedly, the tumor suppressive and anti‐metastatic activity of Samsn1 in 5TGM1 cells were not evidenced following cell administration either intratibially or intravenously to NSG mice." (PMID 32923989, 2020). "POSTN, PPEF1, SAMSN1 and TNFSF13B were upregulated in a great majority of the ccRCC tumours." (PMID 27358011, 2016). "In addition, reduced SAMSN1 expression did not affect the number of metastatic RPMI‐8226 or JJN3 tumor cells in the BM of the non‐injected legs of the mice (p > 0.05, Mann–Whitney U test)." (PMID 32923989, 2020). "Crucially, it was also revealed that the ability of Samsn1 to suppress the outgrowth of disseminated 5TGM1 cells in the BM was absent in immunodeficient NSG mice, suggesting that functional immune cells are required for the tumor suppressor effect of Samsn1 in vivo." (PMID 32923989, 2020). "SAMSN1 overexpression in HMCLs did not significantly inhibit metastasis following intratibial (i.t.)injection of tumor cells in vivo, which contrasted with the significant suppression of metastasis caused by Samsn1 re‐expression in the 5TGM1/KaLwRij i.t. model of MM." (PMID 32923989, 2020). "We also found that a GBM with a MTD >4 cm, and non-clear boundary was more often to be seen in the high SAMSN1 group than in the low SAMSN1 group (p<0.1), possibly suggesting increasing proliferative and infiltrating ability of tumor cells with a higher level of SAMSN1 expression." (PMID 24278465, 2013). "Samsn1 expression was not restricted to the B-cell lineage, so we hypothesized that Samsn1 might influence MM development via effects on additional cell types in the tumor stroma." (PMID 26020268, 2015).
cancer (13 papers, 2013 to 2024). A tumor composed of atypical neoplastic, often pleomorphic cells that invade other tissues. "Cancer development and progression was seen to be affected by Tnfrsf1a, Adrbk2, Pld4, Gnat1 and Samsn1 in other studies." (PMID 34185104, 2021). "The assumption is that Samsn1 neoantigens are being processed and presented on the cancer cell surface bound to MHC class I molecules for recognition by previously primed Samsn1‐epitope specific effector T cells." (PMID 32923989, 2020). "This phenomenon was consistent with Samsn1 either reducing the efficiency of cancer cell migration to the BM or reducing the growth of migrated cancer cells in the BM microenvironment." (PMID 32923989, 2020). "BRD9 inhibition by I-BRD9 in Kasumi-1 cells resulted in lower expression of various cancer- associated genes (CLEC1, DUSP6, FES and SAMSN1)." (PMID 28714904, 2017). "We further integrated our methylation results with RNA-seq data, and we identified 11 genes, including six related to immune functions (AHR, LRFN5, NTRK2, RSPO2, SAMSN1, and TFEC), and three related to cancer (SLC12A5, SORCS1, and TP63)." (PMID 39795948, 2024). "So it is very possible that SAMSN1 could interact with some key molecules in GBM and promote the cancer progression." (PMID 24278465, 2013). "Secondary transplants with any emergent 5TGM1‐Samsn1 cancers could be performed, and they may well have undergone immunoediting and could be less immunogenic and may no longer rejected by Samsn1−/− hosts." (PMID 32923989, 2020). "Without these molecules, the cancer promoting actions of SAMSN1 could not be fully activated." (PMID 24278465, 2013).
infection (3 papers, 2012 to 2023). The state of being infected such as from the introduction of a foreign agent such as serum, vaccine, antigenic substance or organism. "Immune response proteins such as SAMSN1, CCLs, and CXCLs play a vital role in signaling leukocyte migration at the infection site." (PMID 36986315, 2023). "In fact, we only observed two exceptions to this classification at 24 h post-infection: Psme2 (more induced in mutants than in controls), and Samsn1 (repressed in controls, and unaffected in mutant cells)." (PMID 22916300, 2012).
SAMSN1 also shares sentences with these, for which no sentence is quoted: multiple myeloma (6 papers); gastric cancer (4); acute pneumonia (2); coronary atherosclerosis (2); acute coronary syndrome (1); acute myeloid leukemia (1); atrial fibrillation (1); B lymphocytopenia (1); blood cancer (1); breast carcinoma (1); chorioamnionitis (1); colon cancer (1); coronary artery disease (1); coronary artery stenosis (1); diabetic cardiomyopathy (1); diffuse large B-cell lymphoma (1); immune system disease (1); infarction (1); injury (1); intracranial hypertension (1); ischemia (1); liver cancer (1); lung (1); lung adenocarcinoma (1); lung squamous cell carcinoma (1); malignant glioma (1); Obesity (1); Plasmodium falciparum malaria (1); pneumococcal infection (1); psoriasis (1).
A further 2 diseases each share a sentence with SAMSN1 in 1 paper.